ANXA5 (annexin A5)
Diseases named in the same sentence as ANXA5 in open-access papers (continued):
Sharing a sentence is not in itself a finding about the gene and the disease.
osteoporosis (4 papers, 2020 to 2025). A condition of reduced bone mass, with decreased cortical thickness and a decrease in the number and size of the trabeculae of cancellous bone (but normal chemical composition), resulting in increased fracture incidence. "Taken together, these findings demonstrated that AnxA5 contributes to attenuating bone loss and slowing the progression of osteoporosis." (PMID 37940665, 2023). "Candidates such as AnxA5 extracted from MV components provide potential targets to prevent bone loss in osteoporosis." (PMID 37940665, 2023). "The role of MV-derived AnxA5 in mineralization regulation provides new clues for the prevention of bone loss in osteoporosis." (PMID 37940665, 2023). "Through this systematic investigation, we aimed to determine the changes in MVs in osteoporotic progression and demonstrate the importance of AnxA5 in MV-mediated mineralization, thus providing new clues for potential targets for bone loss in osteoporosis from the perspective of MVs." (PMID 37940665, 2023). "Taken together, these findings established a positive relationship between osteoporosis and loss of annexins, particularly AnxA5, which may be crucial for MV-mediated biomineralization." (PMID 37940665, 2023). "Numerous studies have indicated that ANXA5 is able to promote osteoblast differentiation and prevent osteoporosis." (PMID 40342928, 2025). "ANXA5 not only promotes osteogenic differentiation, prevents the occurrence of osteoporosis, and facilitates chondrocyte mineralization and apoptosis but also enhances angiogenesis in the vascular endothelium and protects nerve cells." (PMID 40342928, 2025). "Second, we used recombinant AnxA5 protein instead of AnxA5-expressing MVs to treat osteoporosis due to the difficulty of AnxA5-MV collection." (PMID 37940665, 2023). "Here, we report that annexin A5, an important component of the matrix vesicle membrane, plays a vital role in bone matrix homeostasis in the deterioration of osteoporosis." (PMID 37940665, 2023). "We found that the expression of AnxA2, AnxA5 and AnxA6 was distributed along the edge of cancellous bone where the osteoblasts were distributed, and their expression was lower in the osteoporosis group than in the sham group." (PMID 37940665, 2023). "From histology, we found that AnxA5 injection retained the number of cancellous bone in osteoporotic mice and alleviated the degree of adiposity in the bone marrow of osteoporosis." (PMID 37940665, 2023). "Taken together, these data revealed the importance of annexin A5, originating from adherent MVs of osteoblasts, in bone matrix remodeling of osteoporosis and provided a new strategy for the treatment and intervention of bone loss." (PMID 37940665, 2023). "This evidence identified AnxA5 as a core target in the role of MVs in mediating bone formation and mineralization and provided a potential applicable option in bone mass maintenance in the pathological progression of osteoporosis." (PMID 37940665, 2023). "To determine whether AnxA5 has therapeutic effects on osteoporosis, we intravenously injected AnxA5 recombinant protein into the tails of normal and osteoporotic mice." (PMID 37940665, 2023). "Thus, we did not directly demonstrate the role of MV-derived AnxA5 in protecting against bone loss in osteoporosis." (PMID 37940665, 2023). "We first identified annexin A5 from adherent MVs but not dissociative MVs of osteoblasts and found that it could be sharply decreased in the bone matrix during the occurrence of osteoporosis based on ovariectomized mice." (PMID 37940665, 2023).
glaucoma (3 papers, 2018 to 2024). Increased pressure in the eyeball due to obstruction of the outflow of aqueous humor. "The DARC (Detection of Apoptosing Retinal Cells) project has developed a minimally invasive method using fluorescently-labelled annexin A5 to detect rates of RGC apoptosis in situ in glaucoma patients." (PMID 38297331, 2024). "The DARC (Detection of Apoptosing Retinal Cells) project has developed a minimally invasive method using fluorescent annexin A5 to detect rates of apoptosis in retinal ganglion cells, the key pathological process in glaucoma." (PMID 29914056, 2018). "In glaucoma, the DARC (Detection of Apoptosing Retinal Cells) project has developed a minimally invasive method using fluorescently-labelled annexin A5 to detect rates of apoptosis in RGCs." (PMID 38297331, 2024). "Whether annexin A5-labelled, dying RGCs could still recover or be rescued by removing the glaucoma trigger, like high IOP, has not been studied yet." (PMID 38297331, 2024).
HCMV infection (3 papers, 2011 to 2025). "Annexin A5 was found to be involved in cytomegalovirus infection and influenza virus infection." (PMID 21385394, 2011).
liver disease (3 papers, 2018 to 2022). "Annexin A5 and CK18 have not been previously evaluated in canine liver disease." (PMID 30500850, 2018).
periodontal disease (3 papers, 2022 to 2025). "Among the 92 inflammation-related genes evaluated using the TaqManTM Array Plate Human Inflammation Kit (Thermo Fisher Scientific, Waltham, MA, USA), four genes (TNFSF13B, ITGB2, ANXA5, and ANXA3) showed significant differential expression in patients with active periodontal disease." (PMID 40004451, 2025).
type 2 diabetes mellitus (3 papers, 2022 to 2025). A type of diabetes mellitus that is characterized by insulin resistance or desensitization and increased blood glucose levels. "On the other hand, Annexin A5 was found to play a role in reducing neurotoxicity by interacting with amyloidogenic proteins in the context of neurodegenerative diseases and type II diabetes mellitus." (PMID 39456899, 2024).
atrial fibrillation (2 papers, 2009 to 2024). A disorder characterized by an electrocardiographic finding of a supraventricular arrhythmia characterized by the replacement of consistent P waves by rapid oscillations or fibrillatory waves that vary in size, shape and timing and are accompanied by an irregular ventricular response. "Our study suggests a positive correlation between the ANXA5 gene and the occurrence of atrial fibrillation." (PMID 39170695, 2024).
Autoimmunity (2 papers, 2015 to 2022). The occurrence of an immune reaction against the organism's own cells or tissues. "Individually, S100A9 has many intracellular and extracellular functions, including direct selective inflammatory stimulus-dependent S-nitrosylation of multiple targets, one of which is ANXA5, and acting as a potent amplifier of inflammation in autoimmunity." (PMID 26717306, 2015).
chlamydial infection (2 papers, 2009 to 2019). "Inhibition of the apoptotic recognition of C. pneumoniae infected PMN using PS- masking Annexin A5 significantly lowered the transmission of chlamydial infection to macrophages." (PMID 19547701, 2009).
Cognitive impairment (2 papers, 2020 to 2021). Abnormal cognition is characterized by deficits in thinking, reasoning, or remembering. "We used choroid plexus tissue samples and CSF from mild cognitive impairment (MCI) and AD patients to analyse Aβ accumulation, cell death and annexin A5 levels compared with control subjects." (PMID 32523019, 2020).
Down syndrome (2 papers, 2019 to 2023). "The rest have a different cytogenetic location (TNFSF13B on chromosome 13, whilst ANXA3 and ANXA5 on chromosome 4), which seems to corroborate that Down Syndrome causes impairments to the complete genome." (PMID 31772502, 2019).
inflammatory bowel disease (2 papers, 2024). A spectrum of small and large bowel inflammatory diseases of unknown etiology. "Recent studies have suggested that AnxA5 positively affects inflammatory diseases such as inflammatory bowel disease and non-alcoholic liver fibrosis and may regulate macrophage polarization." (PMID 38904008, 2024).
ischemic stroke (2 papers, 2023 to 2025). A stroke disorder caused by obstruction of blood flow to the brain, due to thrombotic (local blood clot formation) or embolic (due to a blood clot or other material traveling from another site) event. "This investigation demonstrated that the neuron-expressed, plasma membrane-associated Ca2+-binding proteins annexin (Anx) A2, AnxA5, AnxA6, and AnxA7 contributed to neuronal CaP deposition in the mouse model of ischemic stroke." (PMID 39820937, 2025). "This investigation demonstrated that several neuron-expressed annexins, including annexin (Anx) A2, AnxA5, AnxA6, and AnxA7, play a role in the development of acute neuronal CaP formation and deposition in the mouse model of ischemic stroke." (PMID 39820937, 2025). "Ischemic stroke did not cause a substantial change in the relative expression of AnxA2, AnxA5, AnxA6, and AnxA7 in the cortical neurons in reference to sham controls." (PMID 39820937, 2025).
keloid (2 papers, 2016 to 2025). An irregularly shaped, elevated mark on the skin caused by deposits of excessive amounts of collagen during wound healing. "We hypothesize that AnxA5 may be beneficial for treating hypertrophic scars, keloids, and radiation-induced skin injury." (PMID 40871009, 2025).
lung squamous cell carcinoma (2 papers, 2016 to 2022). "In our previous report, ANXA5 was found to be down-regulated in lung squamous cell carcinoma (LUSC), compared with adjacent normal tissues, which is consistent with our result conducted from The Cancer Genome Atlas (TCGA)." (PMID 27684953, 2016).
neuropathies (2 papers, 2017 to 2022). "Anti-hemolysis therapies, such as heme-chelating recombinant hemopexin or EV-neutralizing annexin-A5 may also be tested to treat T2D patients with low-grade IVH or established neuropathy." (PMID 36251660, 2022).
Parkinson disease (2 papers, 2020). A progressive degenerative disorder of the central nervous system characterized by loss of dopamine producing neurons in the substantia nigra and the presence of Lewy bodies in the substantia nigra and locus coeruleus. "In a cell model of Parkinson disease, miR-124-3p overexpression promoted cell viability via suppression of the ANXA5/ERK signaling pathway, which was previously shown to promote apoptosis." (PMID 32244461, 2020). "Levels of annexin A5 were reported reduced in CSF from Parkinson’s disease (PD) patients." (PMID 32523019, 2020).
retinal diseases (2 papers, 2024). "The investigation of PS inhibition by systemically administered ANXV (recombinantly produced human Annexin A5) in patients with RVO is one example of efforts to provide additional safe and effective therapies in the retinal disease space." (PMID 39204083, 2024). "The pharmacologic effects of recombinant human Annexin A5 that might be of relevance to RVO and other retinal diseases include its anti-adherent, anti-inflammatory, anti-thrombotic, and cell-protecting effects." (PMID 39204083, 2024).
acne (1 paper, 2024). An inflammatory process of the sebaceous glands which is characterized by comedones, nodules, papules and/or pustules on the skin. "Through MR analysis and examination of causality directions, 2 proteins (FSTL1 and ANXA5) were causally implicated in acne out of the 14 analyzed." (PMID 39493760, 2024). "Each one-standard deviation increase in the expression levels of FSTL1 and ANXA5 was associated with a 24% and 32% increase in acne incidence, respectively." (PMID 39493760, 2024). "Our study reveals that the expression levels of FSTL1 and ANXA5 in the transcriptome at acne dermal lesions significantly exceed those in the normal control group." (PMID 39493760, 2024). "This exploration successfully identified FSTL1 and ANXA5 as the potential protein targets for acne treatment." (PMID 39493760, 2024). "Furthermore, cohort study results indicate a substantial impact on acne risk, with every one SD increase in the expression of FSTL1 and ANXA5 proteins associated with a 24% and 32% increase in the incidence of acne, respectively." (PMID 39493760, 2024). "The protein group differential analysis indicated that, For acne, the serum levels of FSTL1 and ANXA5 were significantly elevated in patients relative to the control group." (PMID 39493760, 2024). "To date, the relationship between FSTL1, ANXA5, and acne has not been extensively explored in the scientific literature." (PMID 39493760, 2024). "Further RNA-Seq differential analysis found that the expression of ANXA5 and FSTL1 in acne dermal lesions was significantly higher than in non-lesion sites." (PMID 39493760, 2024). "However, the expression of ANXA5 and FSTL1 in acne epidermal lesions was significantly lower than in non-lesion sites." (PMID 39493760, 2024).
aging (1 paper, 2025). A developmental process that is a deterioration and loss of function over time. "Our research indicates that CA is a novel nutritional senomorphic with promising application prospects, and Annexin A5 could be developed as a practical and specific target for precise intervention in aging‐related diseases." (PMID 41476649, 2025).
Atherosclerotic lesion (1 paper, 2014). A lesion associated with atherosclerosis, a multifactorial and multipart progressive disease manifested by the focal development within the arterial wall of lesions, that ranges from the development of a fatty streak, plaque progression, and plaque disruption. "AnxA5 reduced plaque macrophage content both in the intima (59% reduction, P < 0.05) and media (73% reduction, P < 0.01) of advanced atherosclerotic lesions of the carotid artery." (PMID 25214012, 2014).
B-cell acute lymphoblastic leukemia (1 paper, 2025). A neoplasm of lymphoblasts committed to the B-cell lineage, typically composed of small to medium-sized blast cells. "ANXA5 overexpression in B cell acute lymphoblastic leukemia is implicated in glucocorticoid resistance." (PMID 40868343, 2025).
brain infarction (1 paper, 2025). Tissue necrosis in any area of the brain, including the cerebral hemispheres, the cerebellum, and the brain stem. "Further tests showed that administration of AnxA2, AnxA5, AnxA6, or AnxA7 to the healthy mouse brain caused brain CaP deposition, as tested by the Alizarin Red S assay, in association with brain infarction, as detected by the TTC assay." (PMID 39820937, 2025).
depression (1 paper, 2013). "Our preliminary data suggest that plasma annexin A5 levels of the six patients with depression was comparable with controls (data not shown), which might implicate annexin A5 as a biomarker for discriminating between neurodegenerative and non-neurodegenerative diseases." (PMID 23576984, 2013).
dysferlinopathy (1 paper, 2024). "Moreover, we observe significant associations between the protein expression of ANXA1, ANXA2, ANXA4, ANXA5, LMNA, PYGM, and the extent of histopathologic changes in muscle biopsies from patients with dysferlinopathy, validated through immunoblotting and immunofluorescence assays." (PMID 39350328, 2024).
endophthalmitis (1 paper, 2023). An infectious process affecting the internal structures of the eye. "This study found that Annexin A5, cathepsin D, and C5a were significantly downregulated in infected mice compared to uninfected mice, indicating their potential as prospective biomarkers for the diagnosis or prognosis of Staphylococcus aureus endophthalmitis." (PMID 37603522, 2023).
familial Mediterranean fever (1 paper, 2010). Familial Mediterranean fever (FMF) is an autoinflammatory disorder characterized by recurrent short episodes of fever and serositis resulting in pain in the abdomen, chest, joints and muscles. "In the present study we determined the serum levels of apoptotic marker, Annexin A5, in familial Mediterranean fever patients, within an attack and attack-free, in comparison to healthy subjects and assessed the influence of colchicine treatment on this parameter." (PMID 21092278, 2010).
fibromatosis (1 paper, 2021). A poorly circumscribed neoplasm arising from the soft tissues. "ANXA2 and ANXA5 were both under-expressed in the mutant GFs; we anticipate that dysregulated responses of ERS GFs to chronic inflammatory and fibrotic conditions may contribute to the fibromatosis." (PMID 34777248, 2021).
hemorrhage (1 paper, 2023). Loss of blood from the vascular compartment to the exterior or into nonvascular body space as a result of rupture or severance of the blood vessels. "In our study, the mean Annexin A5 level was 16.36±4.47 ng mL-1 in the hemorrhage group, which was found to be statistically significantly higher compared to the other groups." (PMID 37876163, 2023). "The mean Annexin A5 level was 16.36±4.47 ng mL-1 in the hemorrhage group, which was statistically significantly higher compared to the other groups (P=0.002)." (PMID 37876163, 2023). "The mean Annexin A5 level was in the hemorrhage group, which was significantly higher compared to the other groups." (PMID 37876163, 2023).
interstitial lung disease (1 paper, 2025). A diverse group of lung diseases that affect the lung parenchyma. "Increased alveolar soluble ANXA5 was observed in human bronchoalveolar lavage fluids (BALF) with interstitial lung disease, and its expression significantly increased in serum and lung tissues in silica‐exposed mice." (PMID 41476649, 2025).
keratoconus (1 paper, 2026). A degenerative, structural disorder of the eye, characterized by a cone-shaped protrusion of the cornea. "Proteins with potential roles in maintaining epithelial integrity, such as Annexin A5, mucin-like protein 1, and small proline-rich protein 3, were reduced in keratoconus tears, consistent with previous reports of compromised epithelial barrier function in these patients." (PMID 41601845, 2026).
lipidosis (1 paper, 2019). "In addition, we found the maximum amount of SAP and annexin A5 in the sample of atherosclerotic plaques at the stage of lipidosis and fibrosis." (PMID 31703357, 2019).
localized scleroderma (1 paper, 2025). Localized scleroderma is the skin localized form of scleroderma characterized by fibrosis of the skin causing cutaneous plaques or strips. "In this study, recombinant human AnxA5 was administered via subcutaneous injection to treat localized scleroderma." (PMID 40871009, 2025).
pregnancy disorder (1 paper, 2025). A disorder that is related to pregnancy. "Most current studies on ANXA5 mainly concentrate on immune disorders, pregnancy disorders and serve as a biomarker for various diseases as well as apoptosis detection." (PMID 40342928, 2025).
renal dysfunction (1 paper, 2020). "As ischemic renal dysfunction significantly contributes to apoptosis, annexin A5 can be a biomarker for predicting AKI." (PMID 32132597, 2020).
renal fibrosis (1 paper, 2023). A final common manifestation of a wide variety of chronic kidney diseases characterized by glomerulosclerosis and tubulointerstitial fibrosis. "Through PPI network and molecular docking module analyses, CASP3, MMP9, ANXA5, and HSP90AA1 were identified as major pivotal gene targets in renal fibrosis." (PMID 37179298, 2023). "Network pharmacology analysis and experimental results suggest that diosmin ameliorates renal fibrosis by decreasing the expression of CASP3, ANXA5, MMP9, and HSP90AA1." (PMID 37179298, 2023). "Network pharmacology analysis and molecular docking technology were used to explore the potential mechanism of action of diosmin against renal fibrosis, and the key therapeutic targets of diosmin were identified as CASP3, MMP9, ANXA5, and HSP90AA1." (PMID 37179298, 2023). "Therefore, the core genes CASP3, ANXA5, MMP9, and HSP90AA1 may play key roles in the inhibition of the occurrence and development of renal fibrosis." (PMID 37179298, 2023).
tendinopathy (1 paper, 2014). "In ACL, the anti-apoptotic proteins clusterin and annexin A5 were enriched, both of which have previously been identified in tendinopathy." (PMID 24818782, 2014).